INS (insulin)
Diseases named in the same sentence as INS in open-access papers (continued):
Sharing a sentence is not in itself a finding about the gene and the disease.
Hepatic steatosis (continued). "SREBP-1c, the only SREBP isoform induced by insulin, is transcriptionally induced at mRNA as well as the proteolytically activated by insulin, leading to the induction of hepatic lipogenesis pathway and the development of hepatic steatosis." (PMID 36838721, 2023). "Current studies show that the underlying mechanisms responsible for the effects of exercise on insulin resistance and fatty liver are complex and elusive." (PMID 36817440, 2023). "A comparison of groups based on their adherence to MD showed not only a significant reduction in insulin levels, but also found a 36% lower chance of hepatic steatosis among those adhering to a MD." (PMID 37242133, 2023). "We demonstrate that SERT deficient mice show elevated visceral adipose tissue inflammation, insulin resistance and liver steatosis after chronic HFD feeding." (PMID 37520561, 2023). "Taken together, these studies indicate a regulatory function of Kupffer cells on hepatic insulin sensitivity and hepatic steatosis." (PMID 37242206, 2023). "Fatty liver disease leads to hepatocyte steatosis, hepatocyte injury, an inflammatory response, and liver fibrosis, and is closely related to insulin resistance and oxidative stress." (PMID 36978948, 2023). "In contrast, hepatic CES2/Ces2 expressions are considered to prevent fatty liver disease by improving glucose tolerance and insulin sensitivity." (PMID 37339977, 2023). "Physical activity improves insulin sensitivity and fatty liver disease; cardiorespiratory fitness is recommended as an activity that can reduce liver damage." (PMID 36983739, 2023). "It has been observed that a low n-6/n-3 PUFA ratio (4:1) leads to a reduction in ALT, triglycerides, LDL-cholesterol, and an improvement in whole-body insulin sensitivity, favouring the reversion of fatty liver disease." (PMID 37627549, 2023). "Recently, a growing number of studies have suggested the correlation between dysfunctional sphingolipid metabolism and impaired insulin signaling followed by liver steatosis development." (PMID 37892425, 2023). "Fortunately, progress has been made in the study of insulin sensitizers for the treatment of fatty liver disease." (PMID 37745847, 2023). "Eicosapentaenoic acid (C20:5 omega-3) and docosahexaenoic acid (C22:6 omega-3), representative omega-3 PUFAs, have been observed to reduce hepatic lipidosis, improve markers of liver damage, and increase insulin sensitivity." (PMID 36839168, 2023). "Fatty liver disease is a complex physiological process that involves lipid metabolism, insulin resistance, inflammatory response, and gluconeogenesis." (PMID 37740216, 2023). "Several human and animal studies have linked ABCG5/G8 variants and expression with cardiometabolic traits, such as insulin sensitivity, glycemic control, blood pressure status, and fatty liver disease." (PMID 36981027, 2023). "E4 mice evinced significantly improved glucose clearance, lower endogenous insulin secretion, reduced serum triglycerides, attenuated hepatic steatosis and inflammation." (PMID 36012550, 2022). "In contrast, inhibition of the AMPK signaling pathway by AMPK downregulation aggravates insulin resistance and hepatic steatosis under high-fat stimuli." (PMID 36186461, 2022). "While EGCG has previously been shown to attenuate body and liver weights and hepatic steatosis, myricetin has been reported to reduce serum triglycerides, insulin insensitivity and hepatic steatosis." (PMID 35409465, 2022). "Liver steatosis had a statistically significant correlation with fasting insulin (p < 0.05), BMI (p < 0.05), and an inverse correlation with HDL-cholesterol (p < 0.05)." (PMID 35892670, 2022). "Here, we demonstrate that mild mitochondrial uncoupling via CRMP treatment reduces hepatic steatosis and improves hepatic insulin sensitivity in aged HFD‐fed mice." (PMID 35088525, 2022).
Hepatic steatosis (continued). "This gene encodes an enzyme whose deficiency will cause congenital generalized lipodystrophy characterized by severe lipoatrophy, insulin resistance and hepatic steatosis." (PMID 35281825, 2022). "The results show that Phillyrin treatment reduces circulating level of glycerol, decreases hepatic steatosis and improves insulin sensitivity in obese mice." (PMID 36276810, 2022). "Our group demonstrated that the new nutraceutical was able to reduce postprandial and fasting glycemia and insulin levels, which was reflected in enhanced inflammation, hepatic steatosis, and redox homeostasis recovery." (PMID 35326098, 2022). "This also suggests that senescence contributes to the worsening of hepatic steatosis, via both direct mechanisms, and via increased lipogenic action of insulin." (PMID 36072934, 2022). "Some studies show that SAMe deficiency promoted the development of NAFLD in MAT1A knocked-out mice, and supplementation with betaine and taurine to high-fat-diet-induced obese mice improved hepatic steatosis and restored insulin sensitivity." (PMID 35893906, 2022). "Many studies have shown that reducing ROS production improves insulin sensitivity, hyperlipidemia, and hepatic steatosis." (PMID 35990322, 2022). "The synthetic ursodeoxycholic acid-derivate BAR501 also increased insulin sensitivity and reduced hepatic steatosis, inflammation and fibrosis in mice with mild steatohepatitis." (PMID 35807885, 2022). "DCPIB restored glycemic control, reduced hepatic steatosis and improved insulin sensitivity in diabetic mice independently of VRAC." (PMID 36211567, 2022). "The JNK signal transduction pathway is crucial for the negative regulation of insulin signaling, which is considered the major contributor to the development of hepatic steatosis." (PMID 36376950, 2022). "Evidence from a small randomized trial that included biopsy-proven NAFLD patients demonstrated a decrease in the hepatic steatosis (assessed by MRS) as well as improvement in insulin sensitivity (IS)." (PMID 36079070, 2022). "Taken together, we have shown that partial replacement of HFD with KO or CO improved DIO-induced adiposity, glucose homeostasis, insulin resistance, serum lipid profiles, and hepatic steatosis." (PMID 35055664, 2022). "SGLT2 inhibitors are promising new therapies for MAFLD and other cardiovascular diseases such as congestive heart failure; however, it is unclear if they have a direct effect on hepatic steatosis or work through effects on body weight and insulin sensitivity." (PMID 36148775, 2022). "Our previous studies showed that amlexanox significantly improves insulin sensitivity and glucose metabolism, while reducing hepatic steatosis in obese mice." (PMID 35917178, 2022). "β-conglycinin, one of the major storage proteins in soybean, was shown to reduce serum triglycerides, glucose and insulin levels, and prevented high-fat induced fatty liver in mice, and increased blood adiponectin level and insulin sensitivity in Wistar rats." (PMID 35678936, 2022). "Consistent with our previous studies in rodents and non‐human primates, daily oral delivery of CRMP was able to significantly reduce hepatic steatosis and improve hepatic insulin sensitivity due to alterations in hepatic DAG content and PKCε translocation." (PMID 35088525, 2022). "PPARδ and PPARγ pharmacological and genetic enhancement attenuated hepatic steatosis by inducing autophagy dependent hepatic lipolysis and ß-oxidation in mouse livers and primary mouse hepatocytes and improving insulin sensitivity." (PMID 36712976, 2022). "The Western diet feeding induced hepatic steatosis, hyperlipidemia, and partly-altered hepatic insulin pathway in the present rat model for NAFLD." (PMID 36496443, 2022). "These mice indeed display hepatomegaly, an improved glucose tolerance with a decrease glucose hepatic output in response to insulin, hepatic steatosis and a decreased adiposity." (PMID 35409319, 2022).
Hepatic steatosis (continued). "Under a high-fat diet (HFD), they presented higher adiposity, developed hepatic steatosis, and showed higher levels of insulin and hepatic TGs." (PMID 36354755, 2022). "Mediation analysis revealed that the total effect of fatty liver on intraocular pressure was 0.90 (0.81–0.99), with a direct effect of 0.81 (0.71–0.90) and an indirect effect of 0.09 (0.06–0.11) through insulin resistance." (PMID 36364718, 2022). "Due to the hypertriglyceridemia present in fatty liver, visceral adipose tissue increases the production of leptin, which impairs insulin sensitivity, and reduces the level of adiponectin, which stimulates the action of insulin in peripheral tissues." (PMID 35268466, 2022). "Only 71 children completed the trial and showed improvement concerning insulin sensitivity, serum aminotransferases and hepatic steatosis." (PMID 35743870, 2022). "Mechanistically, EV-miRNAs decreased fatty acid and cholesterol biosynthesis pathways in the liver, reducing hepatic steatosis and increasing insulin sensitivity, resulting in decreased glycemia and triglyceridemia." (PMID 36499248, 2022). "In general, both soy protein and isoflavones appear to be effective in lowering liver and blood lipids, improving glucose tolerance and insulin sensitivity and reducing liver steatosis although some inconsistencies exist in the effects of isoflavones." (PMID 35678936, 2022). "They observed improvements in several pathways, such as liver biochemistry and markers of inflammation, hepatic and systemic insulin sensitivity, insulin sensitivity and lipolysis, hepatic de novo lipogenesis, and hepatic steatosis." (PMID 35054924, 2022). "In another study using an animal model, nCGA decreased hepatic steatosis and improved lipid profiles, glucose levels and insulin sensitivity." (PMID 35893859, 2022). "MøFoxO1 KO also resulted in a significant reduction in hepatic expression of Mttp and Apob, 2 key lipid-binding proteins in VLDL-TG production, secondary to the reduction in hepatic steatosis and improvement of insulin sensitivity in HFD-fed MøFoxO1-KO mice." (PMID 35700043, 2022). "Accordingly, ob/ob mice are obese, hyperphagic, inactive, hyperinsulinemic, hyperglycemic, hyperlipidemic, resistant to insulin, and develop intestinal bacterial overgrowth and spontaneous liver steatosis." (PMID 36555433, 2022). "In Black Americans, the lower prevalence of fatty liver persisted after controlling for both body mass index and insulin resistance." (PMID 36555867, 2022). "These mice exhibited hepatic steatosis, hyperleptinemia, and high levels of TGs and insulin in plasma." (PMID 36354755, 2022). "We discovered that an EE improved glucose metabolism, increased insulin signaling in liver, and reduced hepatic steatosis and inflammation, and increased lipolysis and browning in the white adipose tissue of high-fat diet (HFD)-fed mice." (PMID 35112705, 2022). "Liver enzyme activity (ALT, AST, GGT), total bilirubin, lipids fractions, apolipoprotein A1 (ApoA1), α-2-macroglobulin (α2M), haptoglobin (Hp), fasting blood glucose, and fasting insulin are used to generate liver steatosis scores." (PMID 35268466, 2022). "Evidence shows that drinking alcohol impairs the liver of drinkers and produces steatohepatitis and fatty liver alcohol, which elevate hepatic IR and reduce hepatic insulin sensitivity." (PMID 35449023, 2022). "Testosterone replacement therapy in hypogonadal men with metabolic syndrome had favorable effects on hepatic steatosis, insulin sensitivity, and glucose control." (PMID 36482993, 2022). "Melatonin-mediated antioxidant activity further improved insulin resistance and hepatic steatosis in diet-related obesity." (PMID 36207302, 2022). "Myeloid/macrophage-specific KO models such as IKK-β or CCR2 that impair inflammatory responses in Kupffer cells show attenuation of hepatic insulin resistance in the setting of high-fat feeding, despite the full development of hepatic steatosis." (PMID 36177037, 2022).
Hepatic steatosis (continued). "In conclusion, the lipidomics results of this research proved QGD inhibited hepatic steatosis mainly by reducing hepatic insulin resistance and triglyceride biosynthesis." (PMID 36452137, 2022). "ApoE KO mice at 12 months of age have increased serum levels of triglycerides, glucose, and insulin, in addition to hepatic steatosis and increased plasma levels of liver enzymes, demonstrating liver damage." (PMID 36286035, 2022). "Adropin improves insulin sensitivity, hepatic steatosis, whole-body adiposity and insulin resistance." (PMID 35740032, 2022). "In genetic and diet-induced obese mouse models, hepatic miR-125a expression was decreased, whereas, miR-125a overexpression improved insulin sensitivity and alleviated hepatic steatosis in HFD-fed mice." (PMID 36360201, 2022). "Foods with a high glycemic index induce hepatic steatosis, particularly in insulin-resistant individuals." (PMID 35055797, 2022). "The synthetic cholic acid-derivate INT-777 improved insulin sensitivity and hepatic steatosis in mouse models." (PMID 35807885, 2022). "Another study demonstrated that exercise significantly reduced serum ALT levels in NAFLD patients, while improving hepatic steatosis and insulin sensitivity." (PMID 36605939, 2022). "Recent studies have shown that autophagy regulates lipid metabolism; autophagy is inhibited in the livers of HFD-induced obese mice, and restoration of autophagy improves hepatic steatosis and increases insulin sensitivity." (PMID 36451739, 2022). "In the laboratory results, the mean levels of AST, ALT, triglyceride, and insulin were observed to increase as the fatty liver grade increases." (PMID 35444966, 2022). "When the capacity of adipose tissue to store energy was overloaded, hepatocytes store the extra lipids, leading to ectopic fat accumulation, insulin resistance, and hepatic steatosis." (PMID 36532560, 2022). "Second, effects of CD44 on hepatic steatosis and insulin sensitivity were only observed in male C57BL/6J mice." (PMID 35410390, 2022). "The result of a symbiosis between cytokines and the transcription factor increased insulin sensitivity, reduced blood glucose and insulin, and improved liver steatosis and antioxidant activity." (PMID 35326098, 2022). "In in vivo experiments using hepatocyte-specific GHR knockdown (aHepGHRkd) mice, hepatic steatosis rapidly developed independently of systemic insulin sensitivity and lipolysis." (PMID 36699040, 2022). "The strength in our findings regarding hepatic steatosis and insulin sensitivity is the use of several insulin sensitivity indices, recognizing that HOMA2S primarily is an insulin sensitivity-surrogate evaluating NAFLD for patients without T2D." (PMID 36336684, 2022). "11β-HSD1 converts the inactive glucocorticoid cortisone to its active form cortisol, and 11β-Hsd1–/– mice have a beneficial metabolic phenotype with improved insulin sensitivity and protection against hepatic steatosis." (PMID 35318963, 2022). "In most of the studies, it is notable that EMPA improved hepatic lipid metabolism, hepatic steatosis, insulin sensitivity, fasting glucose level, and reduced body weight in some studies." (PMID 36168335, 2022). "The plasma LEAP2 levels were reported to be positively correlated with age, BMI, and fasting insulin in patients with hepatic steatosis, but negatively correlated with acyl ghrelin." (PMID 35521798, 2022). "In a mouse model of diet‐induced T2D, imeglimin enhanced the actions of intraperitoneal injection of insulin on glycaemia, improved insulin signalling in muscle and liver, and reduced hepatic steatosis." (PMID 36239048, 2022). "These animals showed improved energy expenditure, insulin sensitivity, glucose tolerance, and decreased hepatic steatosis, indicating that the adipocyte-autonomous effects of ceramides affect systemic metabolic function." (PMID 35789435, 2022).
Hepatic steatosis (continued). "Intrasubcutaneous adipose tissue injections of anti-miR-149-3p lentiviral vectors ameliorated hepatic steatosis and whole-body insulin sensitivity by increasing Prdm16 gene expression, and suppressing proinflammatory genes." (PMID 36360201, 2022). "The AGPAT2 deficient mice are hyperglycemic, hyperinsulinemic, hypoleptinemic, insulin-resistant and display liver steatosis." (PMID 35250856, 2022). "In animal models of hepatic steatosis, the ability of insulin to inhibit hepatic gluconeogenesis is diminished even when muscle insulin resistance is not significantly altered." (PMID 35968500, 2022). "High-fat diet (HFD) or high-sucrose diet is widely used for inducing metabolic disorders characterized by increased body weight, insulin resistance, hepatic steatosis, and alteration of gut microbiome." (PMID 35928832, 2022). "In our study, protection from pre‐steatotic lipidosis paralleled the effect of these treatments on circulating insulin, which affects hepatic steatosis through regulation of Fasn (hepatic fatty acid synthase) expression." (PMID 35986566, 2022). "Supplementation with n-3 PUFAs inhibited lipogenesis, attenuated hepatic oxidative stress, decreased inflammation and increased insulin sensitivity, further to preserve hepatic architecture and prevent hepatic steatosis." (PMID 35958253, 2022). "From a clinical point of view, it is suggested that patients with PCOS should be evaluated for the presence of hepatic steatosis, especially those with reduced insulin sensitivity and/or hyperandrogenism." (PMID 35576937, 2022). "In the present study, along with improved insulin sensitivity, hepatic steatosis induced by the HFD was ameliorated in seabuckthorn freeze-dried powder-fed mice." (PMID 35889860, 2022). "In contrast, CCL5 KO mice were more insulin resistant and had severe hepatic steatosis than WT mice under obese conditions." (PMID 36713454, 2022). "Angptl8-ASO mice exhibited a significant reduction in liver steatosis and improved insulin sensitivity compared to control-ASO treated mice." (PMID 35295579, 2022). "In contrast, fat-specific Blnc1 transgenic mice (Blnc1 Tg mice) exhibited much lower plasma insulin concentrations, improved insulin sensitivity and glucose tolerance as well as ameliorated hepatic steatosis." (PMID 36555704, 2022). "Zn deficiency caused by chronic liver disease also evokes metabolic alterations such as insulin resistance, Fe overload and hepatic steatosis." (PMID 35743260, 2022). "Moreover, hepatic steatosis—a risk factor for accelerated fibrogenesis and development of hepatocellular carcinoma —is recognized as the liver manifestation of MetS, and hepatic steatosis and MetS share pathophysiological mechanisms, with insulin resistance playing a pivotal role." (PMID 36294456, 2022). "Activation of classical BAT and browning of WAT are associated with a favourable metabolic status including improved insulin sensitivity and reduced fatty liver disease." (PMID 34846543, 2022). "Effective eradication of HCV improves insulin resistance and liver steatosis related to viral infection but cannot resolve fatty liver disease and impaired insulin response as a component of the metabolic syndrome." (PMID 36551908, 2022). "PAMPs are recognized by PRRs at low concentrations under physiologic conditions, but this effect increases in the presence of LPS, which subsequently provokes an inflammatory reaction, insulin resistance, fatty liver disease, retinopathy and nephropathy." (PMID 36406423, 2022). "This occurred in parallel with liver steatosis and increased circulating levels of insulin, but before any significant increase in body weight and blood glucose level." (PMID 35888749, 2022). "The ‘portal theory’ suggested that, in obese patients, venous drainage of increasing amounts of pro-inflammatory factors and free fatty acids from VAT to the liver via the portal system favors the development of hepatic insulin resistance and liver steatosis." (PMID 34638880, 2021).